CXCL3 (C-X-C motif chemokine ligand 3)
Diseases named in the same sentence as CXCL3 in open-access papers (continued):
Sharing a sentence is not in itself a finding about the gene and the disease.
prostate carcinoma (16 papers, 2016 to 2023). A carcinoma that arises from epithelial cells of the prostate gland. "Overexpression of CXCL3 can increase the risk of prostate cancer tumor formation and plays multiple roles in the progression and metastasis of this cancer." (PMID 35802745, 2022). "A study has shown that CXCL3 overexpression significantly promoted the migration of prostate cancer cells and increased the expression of the tumor-associated Erk in prostate cancer cells." (PMID 36345403, 2022). "Overexpressed CXCL3 can heighten the risk of tumorigenesis in prostate cancer and cervical cancer." (PMID 35802745, 2022). "Some studies have shown that CXCL3 promotes prostate cancer cell proliferation and migration by upregulating p-ERK1/2, p-Akt, and Bcl2 and downregulating Bax." (PMID 37445610, 2023). "In a previous study, we found that the proliferation and migration of prostate cancer cells show obvious dose-dependent effect with CXCL3 concentration increased." (PMID 38031087, 2023). "Accordingly, our previous studies also revealed that CXCL3 facilities the malignant behaviors of tumor cells in cervical cancer and prostate cancer via activation of the MAPK/ERK signaling pathway." (PMID 38031087, 2023). "For example, it has been suggested that that CXCL3 was highly expressed in prostate cancer and high CXCL3 expression was closely related to the poor prognosis of patients." (PMID 34870709, 2021). "CXCL3 plays a predominant role in the tumorigenicity of prostate cancer cells and is upregulated in prostate cancer." (PMID 32337262, 2020). "Additional studies are required to ascertain the biological role of ESM-1 in prostate cancer cells and the link with the expression of CXCL3." (PMID 28533735, 2017). "CXCL3 has been found previously over-expressed in the aggressive PC-3 cell line and its tissue expression correlates with prostate cancer metastasis." (PMID 28533735, 2017). "Additional studies are required to determine the mechanisms underlying the decreased expression of CXCL3 in endocan siRNA silenced PC-3 cells, and more research is needed to ascertain the biological role of ESM-1 in prostate cancer." (PMID 28533735, 2017). "Other studies showed that CXCL3 is involved in migration and invasion of trophoblasts in the pathogenesis of preeclampsia and is involved in the proliferation and migration of prostate cancer cells." (PMID 32986377, 2020). "On the other hand, exogenous CXCL3 enhanced migration of prostate cancer cells." (PMID 29535419, 2018). "Nagaya and co-workers identified higher expression of the CXC chemokine signaling genes, including CXCL1, CXCL3, CXCL6, CXCR1 and CXCR2 in prostate cancer bone metastases." (PMID 35328625, 2022). "The overexpression of CXCL3 and its receptor CXCR2 promoted the proliferation and migration of cancer cells by regulating the expression of genes, including ERK, BAX, TP73, and NDRG3, which enhance the oncogenic potential of prostate cancer." (PMID 30686982, 2018). "CXCL3 and its receptor CXCR2 have been recently found overexpressed in prostate cancer cells, prostate epithelial cells and prostate cancer tissues, which may implicate a role for this chemokine in prostate cancer progression and metastasis." (PMID 28533735, 2017). "CXCL3 has been shown to act as a chemoattractant for neutrophils to areas of brain injury and for cerebellar progenitor cells, while it is not clear for prostate cancer cells if this chemokine is chemoattractant or not." (PMID 28533735, 2017).
COVID-19 (15 papers, 2020 to 2025). A disease caused by infection with severe acute respiratory syndrome coronavirus 2. "The mouse-Geneformer predicted that the activation of genes Cxcl3 and Ccr4 would induce a similar transition towards COVID-19-infected cells." (PMID 40106407, 2025). "Additionally, CXCL3, a member of the CXC-type chemokine family, is known to be involved in the development and progression of various types of cancer and has also been linked to COVID-19." (PMID 37662846, 2023). "A higher expression of chemokines (CXCL1, CXCL2, CXCL3, CXCL8 and CXCL16) were also found in the CD4+ TCM and Classical Monocytes in the COVID-19 patients." (PMID 36532041, 2022). "As notable difference, strong induction of neutrophil-recruiting chemokines targeting CXC chemokine receptor (CXCR) 2, such as CXCL1, CXCL3, CXCL6, and CXCL8, were found only in human basal and secretory cells with severe COVID-19 but were absent in moderately-ill Syrian hamsters." (PMID 34381043, 2021).
pancreatic cancer (15 papers, 2016 to 2025). "At the transcript level, mRNA expression of Ccl2, Ccl7, Cxcl1, Cxcl3, and Csf2 was markedly downregulated in Ccn1‐deficient pancreatic tumors, whereas Cxcl5, Csf1, and Csf3 expression remained unchanged, and Ccl20 mRNA was elevated." (PMID 40287974, 2025). "IL-33-activated M2 TAMs in pancreatic cancers led to high production of CXCL3 and conferred fibroblast-to-myofibroblast transformation via CXCL3-CXCR2 signalling." (PMID 38303024, 2024). "Cancer cell-derived sST2 enhances tumor growth through upregulation of CXCL3 via inhibition of IL-33-ST2L signaling in the tumor microenvironment of pancreatic cancer." (PMID 32340025, 2020). "In addition, it has been shown that type III collagen is required for the metastasis of pancreatic cancer, while CXCL3 is the factor in pancreatic cancer that enhances collagen III expression by promoting cancer-associated fibroblasts transformation." (PMID 36612163, 2022). "In pancreatic cancer, TAM-derived C-X-C motif chemokine ligand 3 (CXCL3) targets CAFs’ C-X-C motif chemokine receptor 2 (CCR2) to mediate CAF-myofibroblasts (myCAF) transition, subsequent type III collagen generation and tumor metastasis." (PMID 36906534, 2023). "The data showed that most of chemokines, such as CX3CL1, CXCL16, CXCL3, CXCL9, and CXCL5, were significantly high expressed in pancreatic tumor tissues compared to normal tissues." (PMID 35478937, 2022). "Other members of the C-X-C motif chemokine family were found to be upregulated in pancreatic cancer cells after Rintatolimod treatment, like CXCL 1, CXCL2, CXCL3, CXCL8 (IL-8), CXCL11, CXCL14, and CXCL16." (PMID 34207861, 2021). "Furthermore, senescence-induced pancreatic stellate cells secrete CXCL1, CXCL2, and CXCL3, and blockade of the CXCR2 axis suppresses pancreatic cancer cell proliferation." (PMID 41155662, 2025). "Furthermore, we identified CXCL1, CXCL2, and CXCL3 as SASP factors secreted by senescence-induced hPSCs, and the inhibition of the CXCLs/CXCR2 axis attenuated their stimulating effects on the proliferation and migration of pancreatic cancer cells." (PMID 36012531, 2022).
cervical cancer (13 papers, 2020 to 2025). A primary or metastatic malignant neoplasm involving the cervix. "Our recent study also reported that the protein expression level of CXCL3 in cervical cancer tissues was significantly higher than that in normal cervical tissues, and high CXCL3 level was positively correlated with high-risk stage of patients." (PMID 34870709, 2021). "Our previous study in cervical cancer revealed that CXCL3 secreted by both tumor and stromal cells can enhance malignant behaviours through both autocrine and paracrine signalling." (PMID 41259383, 2025). "For example, a study by Leonardo Fernandez-Avila reported that CXCL3 expression was significantly higher in cervical cancer tissues compared to normal cervical tissues." (PMID 40517358, 2025). "Solamargine alleviated proliferation and metastasis of cervical cancer cells by blocking the CXCL3-mediated Erk signaling pathway." (PMID 36345403, 2022). "Collectively, our present study suggests that solamargine alleviated proliferation, migration, and invasion of cervical cancer cells by blocking the CXCL3-mediated Erk signaling pathway, and solamargine inhibited the tumor growth of mice in vivo." (PMID 36345403, 2022). "In our subsequent experiments, we found that the expression of CXCL3 in cervical cancer cells positively correlates with cell proliferation, migration, invasion, and the expression of p-Erk1/2." (PMID 36345403, 2022). "Our previous studies also showed that CXCL3, while being less expressed in normal cervix tissues, is strongly expressed in cervix cancer tissues, of which metastatic cervix cancer tissues had the highest expression of CXCL3." (PMID 34870709, 2021). "Additionally, cervical cancer cells with elevated CXCL3 expression can enhance the autonomous proliferation and migration abilities of cancer cells, leading to an overall increase in cell count." (PMID 38275602, 2024). "Furthermore, the administration of exogenous CXCL3 or CXCL5 on cervical cancer cell lines contributes to proliferation and migration." (PMID 37626777, 2023). "CXCL3 overexpression abrogated the antitumor effect of solamargine on cervical cancer cells." (PMID 36345403, 2022). "Moreover, using an in vivo model of cervical cancer, our research group and others have demonstrated the expression of a set of chemokine genes (Cxcl1, Cxcl2, Cxcl3, and Cxcl5) in stromal and epithelial cancer cells, revealing biological crosstalk in cervical carcinogenesis." (PMID 37626777, 2023). "Epiregulin was positively correlated with most chemokines, such as CXCL1, CXCL2, CXCL3, CXCL5, CXCL6, CXCL8, and CCL20, in most types of cancer, including cervical cancer." (PMID 37020674, 2023). "This study revealed that the presence of HPV16 and 18 oncogenes significantly alter the expression of CCL28, CXCL1, CXCL2, CXCL3, CXCL6, CXCL8, CXCL10, and CXCL11; overexpression of those chemokines was also confirmed in cervical cancer biopsies." (PMID 37893029, 2023). "The inhibition of the Erk signaling pathway restored the inhibiting role of solamargine which interfered with CXCL3 overexpression, in invasion, migration, and expressions of MMP-2 and MMP-9 in cervical cancer cells." (PMID 36345403, 2022). "Our results revealed that expression of CXCL1, CXCL2, CXCL3, and CXCL8 increases in the presence of E6/E7 of HPV16 and 18, are overexpressed in CC biopsies, and that their higher expression is related to a worse prognostic survival in cervical cancer." (PMID 37893029, 2023). "Mechanically, to explore whether solamargine regulates the Erk pathway by targeting a specific mRNA, we selected genes reported in recent years to regulate the Erk pathway in cervical cancer, including PBK, RACK1, CXCL3, TRIP4, and SEMA3C, for study." (PMID 36345403, 2022).
cervical cancer (continued). "In order to investigate whether solamargine regulates the Erk signaling pathway by modulating target mRNAs, we screened out genes that regulate this pathway in cervical cancer including PBK, RACK1, CXCL3, TRIP4, and SEMA3C, which have been reported in the literature in recent years." (PMID 36345403, 2022). "Based on available findings that the involvement of CXCL3 depletion in the anticancer mechanism of solamargine might be entwined with the depression of the Erk signaling pathway, we applied PD98059 to block Erk1/2 in cervical cancer cells in a follow-up study and obtained more intuitive results." (PMID 36345403, 2022).
hepatocellular carcinoma (11 papers, 2016 to 2025). A malignant tumor that arises from hepatocytes. "The results showed that CXCL3 was significantly upregulated in hepatocellular carcinoma tissues and associated with reduced overall survival in patients." (PMID 41259383, 2025). "In hepatocellular carcinoma, the up-regulation of CXCL3 expression is associated with a poor prognosis." (PMID 34870709, 2021). "CXCL3, a member of the CXC chemokine family, has been increasingly implicated in the progression of various cancers, including hepatocellular carcinoma, due to its role in immune and inflammatory responses within the tumor microenvironment." (PMID 41259383, 2025). "Upregulated CD133 then acted as an upstream activator of CXCL3 and stimulated the growth of hepatocellular carcinoma cells." (PMID 38532366, 2024). "Although the chemotactic cytokine CXCL3 is thought to play an important role in tumor initiation and invasion, little is known about its function in hepatocellular carcinoma (HCC)." (PMID 27255419, 2016). "This study provides a new direction for the treatment of hepatoma (utilizing the inhibitory effects of lingonberry extract on the chemokine CXCL3), offers new insight into the study of lingonberry’s antihepatoma properties, and provides a basis for the development of pilot antitumor drugs." (PMID 35802745, 2022). "There has been little research into whether CXCL3 is expressed in hepatocellular carcinoma, and more work is needed to verify if CXCL3 overexpression is a potential tumor marker." (PMID 35802745, 2022).
lung carcinoma (11 papers, 2014 to 2025). "Our results demonstrated that metformin drug resistance increases the expression of proinflammatory and invasive genes, including BMP5, CXCL3, VCAM1, and POSTN, in A549 lung cancer cells." (PMID 37239373, 2023). "Lung cancer cells can induce macrophage infiltration by increasing the production of CCL2 and CXCL3." (PMID 34616731, 2021). "TREM2 has been reported to promote macrophage polarization from M1 to M2 via the NF-κB/CXCL3 and JAK-STAT pathways, and in lung cancer, TREM2+ macrophages were associated with a lack of NK cells and their dysfunction." (PMID 39776914, 2024). "Furthermore, preclinical studies from NSCLC animal models show that lung cancer cells can induce the macrophage infiltration through increasing CCL2 and CXCL3 production of NSCLC cells." (PMID 32356397, 2020). "Unlike our results, multiple studies have shown that CXCL2, CXCL3, CXC12, and CXC16 were highly expressed in lung cancer tissues and are essential for tumor growth." (PMID 35844446, 2022).
melanoma (11 papers, 2011 to 2025). A malignant, usually aggressive tumor composed of atypical, neoplastic melanocytes. "CXCL3 is highly upregulated during esophageal carcinogenesis and contributes to vascular invasion in gastric cancer and human melanoma." (PMID 37445610, 2023). "The reduction in the levels of chemokines CXCL1, CXCL2 and CXCL3 in melanoma results in a decrease in tumor angiogenesis and tumor growth, suggesting the importance of these chemokines in angiogenesis." (PMID 24259307, 2013). "Studies using melanoma tumour models support the role of CXCL1, CXCL2, and CXCL3 in mediating tumour angiogenesis and levels of all three chemokines are highly expressed in melanoma tumours." (PMID 21298036, 2011). "Also, the chemokines CXCL1, CXCL2 and CXCL3 have been shown to play a role in the growth of pancreatic cancer, melanoma, lung cancer, adenocarcinoma and gastric cancer." (PMID 24259307, 2013). "CXCL3 belongs to the CXC chemokine family and was initially identified for its expression in human malignant melanoma cells; it is also referred to as melanoma growth-stimulatory activity alpha." (PMID 41259383, 2025). "The chemokines belonging to the growth-related oncogene (GRO) subgroup of CXC chemokines, GRO-α/CXCL1, GRO-β/CXCL2, GRO-γ/CXCL3, were first identified as growth factors of melanoma cell lines, before being attributed neutrophil chemotactic activity." (PMID 34503058, 2021). "GRO chemokines that are expressed during melanoma tumours, and are essential for wound healing activities, comprise three highly similar proteins known as GRO-α (CXCL1), GRO-β (CXCL2) and GRO-γ (CXCL3)." (PMID 28989790, 2017). "Malignant melanoma expresses and secretes various CXC chemokines, including CXCL1, CXCL2, CXCL3 (GRO family chemokines) and CXCL8 (IL-8)." (PMID 28129639, 2017). "Presented here analysis demonstrated that melanoma cells secrete different levels CXCL1 and CXCL8 and rather high levels of CXCL2 and CXCL3 chemokines." (PMID 28129639, 2017). "However, CXCL1, CXCL2, CXCL3, CXCL5 and CXCL8 mRNAs were significantly upregulated in melanoma samples compared to benign nevi." (PMID 37270599, 2023). "In studies using neuroblastoma and melanoma murine models, the absence of CD200/CD200R signaling (using CD200R- mice) caused TAMCs to upregulate CCL24 and CCL8 levels but downregulate the production of CXCL3, CXCL2, and CCL3." (PMID 38137547, 2023). "Thus, the production of CCL24 and CCL8, and the reduction of CXCL3, CXCL2, and CCL3 in TAMCs, explain why mice lacking intact CD200/CD200R signaling more potently rejected neuroblastoma and melanoma tumors relative to wild-type conditions." (PMID 38137547, 2023).
asthma (10 papers, 2015 to 2025). "Our findings revealed that the macrophage-derived Dectin-1/caspase-11/GSDMD pathway exhibited a pivotal pathogenic role in asthma via enhancing neutrophil migration through CXCL1/CXCL3/CXCL5-CXCR2 axis." (PMID 38459541, 2024). "Many genes, including Il33, Cxcl5, Cxcl15, Ccl20, Cxcl3, Cxcl1, C3, and Pfn1, which have been linked to asthma pathogenesis, showed a cell type-specific response to HDM." (PMID 35627266, 2022). "The IL-4/IL-13/STAT6 pathway induces expression of inflammatory chemokines such as CCL11, CXCL1, and CXCL3 and is a central pathway in the pathophysiology of asthma, especially airway hyperresponsiveness." (PMID 35281012, 2022). "Inhibition of Cxcl3 in a mouse model of RV-induced exacerbation of asthma decreased the accumulation of Cxcr2+ neutrophils." (PMID 34557202, 2021). "In autoimmune diseases, CXCL3-induced migration becomes exclusively CXCR1-dependent, which underlines the significance of CXCR1 in the pathogenesis of airway remodeling associated with asthma." (PMID 37709757, 2023). "Our study found that Dectin-1/caspase-11 activation in asthma is not only related to CXCL1, but also related to the secretion of CXCL3 and CXCL5." (PMID 38459541, 2024). "They found that gene signature profiles of Th2 (IL-13, IL-4) and Th17 (CXCL1, CXCL2, CXCL3, IL-8, CSF3) immune responses were inversely correlated in these samples suggesting a reciprocal regulation of these two pathways in asthma." (PMID 26561853, 2015). "Therefore, our study suggested that Dectin-1/caspase-11-mediated macrophage pyroptosis promotes neutrophil airway infiltration in asthma, which depends on the secretion of chemokines such as CXCL1, CXCL3 and CXCL5." (PMID 38459541, 2024).
psoriasis (10 papers, 2018 to 2025). An autoimmune condition characterized by red, well-delineated plaques with silvery scales that are usually on the extensor surfaces and scalp. "Fibroblasts produced a number of chemokines (CCL13, CCL19, CCL2, CCL8, CXCL1, CXCL12, CXCL2, CXCL3) that linked to receptors expressed by myeloid cells and T cells, suggesting an important role for fibroblasts in recruiting immune cells in psoriasis." (PMID 37308489, 2023). "WY14643 treatment significantly downregulated psoriasis‐associated inflammatory cytokines and chemokines (Il17a, Il1b, Cxcl1, Cxcl2, Cxcl3, Cxcl15, and Csf3) as well as the antimicrobial peptides S100a8 and S100a9 in IMQ‐induced skin lesions at the transcriptional level." (PMID 40878384, 2025). "Here, the transcriptional levels of IL-6, IL-23p19, and CXCL-3 were elevated in the psoriasis-like mouse model, and this effect was reduced more in the GC group." (PMID 38139164, 2023). "In support of the Role of IL-17A in the Psoriasis Pathway, CXCL1, CXCL3, CXCL6, S100A8, S100A9, and CCL20 in the shared signature were all upregulated in both psoriatic skin and colon lesional tissues." (PMID 36396672, 2022). "Notably, the “Role of IL-17A in Psoriasis” (T2, −log(FDR) = 1.67) pathway was enriched, in which downregulated CXCL3, IL-8, S100A8, S100A9, IL17RA and CXCL1 expression was observed." (PMID 29871627, 2018). "RT-qPCR experiments further confirmed that CXCL16 expression was significantly elevated in MDMs from psoriasis patients compared to healthy controls, while no statistical differences were observed for CXCL1, CXCL3, and CXCL5." (PMID 40722833, 2025).